FGF2 (fibroblast growth factor 2)
Diseases named in the same sentence as FGF2 in open-access papers (continued):
Sharing a sentence is not in itself a finding about the gene and the disease.
Anxiety (30 papers, 2013 to 2026). Intense feelings of nervousness, tension, or panic often arise in response to interpersonal stresses. "Our in vivo data demonstrated that FGF2 restoration recover neuroligin 1-dependent glutamatergic synaptogenesis, inhibiting the progression of spatial memory loss, anxiety, and depressive mood." (PMID 35562616, 2022). "These include studies showing induction of depressive-like behavior following IGF-1 deficiency, decreased depressive- and anxiety-like behavior after chronic FGF-2 treatment, and improved mood function following peripheral BDNF administration." (PMID 33269095, 2020). "More recently, FGF2 has also been implicated in anxiety and depressive behaviors, both in rodent models and in human studies." (PMID 30273396, 2018). "Although FGF2 has been widely implicated in anxiety and depressive-like behavior, FGF2 levels in response to the CVS model currently employed have not been previously measured." (PMID 30273396, 2018). "An additional study showed that human participants with low salivary fgf2 exhibited significantly heightened skin conductance responses to a conditioned stimulus during a fear conditioning test, leading to the conclusion that low fgf2 is associated with an increase in anxiety in humans." (PMID 35599764, 2022). "People with reduced FGF-2 reactivity in response to stress may have a reduced physiological ability to cope with stress, which places them at an increased risk of developing anxiety." (PMID 33535653, 2021). "In addition to a role for FGF2 in the display of depressive and anxiety behaviors, several studies have linked FGF2 to the therapeutic effects of anti-depressant treatments such as SSRIs." (PMID 30273396, 2018). "It should be noted, however, that other growth factors (BDNF and IGF-1) exert similar neuromodulatory effects as FGF2 on anxiety-related behaviour, as do genetic and environmental factors." (PMID 33860438, 2021). "Knockdown of hippocampal FGF2 activity increases anxiety in naïve rats, and FGF2 treatment reduces anxiety in highly anxious rats." (PMID 33860438, 2021). "The FGF2 knockdown in the hippocampus of rats by short-hairpin RNA silencing increases anxiety behavior." (PMID 30804785, 2019). "Because we have previously shown that the effects of FGF2 administration on anxiety behavior are mediated through FGF2-induced GR upregulation, we quantified hippocampal levels of FGF2 and GR using q-RT-PCR." (PMID 30273396, 2018). "Work from the Akil laboratory demonstrated that FGF2 shows anxiolytic properties in rats bred for high- anxiety and we have previously shown that depletion of the FGF2 gene increases anxiety behavior and HPA activity." (PMID 30273396, 2018). "Results showed that fluoxetine reversed the effects of CVS on depressive and anxiety behaviours in wild-type mice only, suggesting that the FGF2 gene is indeed necessary for the therapeutic effects of fluoxetine." (PMID 30273396, 2018). "We have previously shown that the effects of FGF2 administration on anxiety behavior were mediated through FGF2’s upregulation of hippocampal glucocorticoid receptor expression." (PMID 30273396, 2018). "Expression of FGF2, predominantly expressed in astrocytes, is decreased in rats selectively bred for high anxiety." (PMID 26733803, 2015). "Peripheral administration of FGF2 to rats with endogenously high levels of anxiety was found to reduce anxiety-like behaviors, while lentiviral shRNA-mediated knockdown of FGF2 in rat hippocampus increased anxiety-like behaviors." (PMID 24672476, 2014). "Studies in the animal models show that FGF2, which is low in depressed human brains, serves as a natural anti-depressant and anti-anxiety agent that is present in all brains, but differences in its activity can modify mood." (PMID 23497694, 2013). "While FGF-2 has been identified for potential use as a biomarker for anxiety and trauma." (PMID 39595087, 2024).
Anxiety (continued). "There are many different interactions of FGF ligands and FGFRs, such that specific roles for FGF ligands—such as FGF17 in social behavior, FGF22 in anhedonia-like behavior, or FGF2 or FGF8 in anxiety-like behavior—leaves undetermined what receptors and cells mediate these effects." (PMID 36906620, 2023). "Therefore, enhanced FGF2 expression observed in the amygdala should motivate studies of FGF2 signaling in the context of ethanol modulation of anxiety-like behaviors." (PMID 35706690, 2022). "In fact, FGF2 is down-regulated in rats showing high spontaneous anxiety." (PMID 33860438, 2021). "Further investigation revealed that knocking down FGF2 expression in prefrontal cortical OPCs recapitulated the anxiety-like phenotype and thus suggested that genetic and stress-induced loss of OPCs triggered the emergence of depressive-like behaviors by reducing the secretion of FGF2." (PMID 33144710, 2021). "High-anxiety rats have lower levels of FGF2 mRNA in hippocampus compared with low-anxiety ones." (PMID 30804785, 2019). "The correlation between FGF2 and anxiety is most often elucidated." (PMID 30804785, 2019). "Moreover, peripheral FGF2 administration both in early-life and in adulthood of rats significantly reduces anxiety behavior." (PMID 30804785, 2019). "This suggests that FGF2’s unique contribution to the pathology and treatment of anxiety and depressive-like behaviors may be better understood by examining the cells that are targeted, astroglia." (PMID 30273396, 2018). "Pearson correlations between GR and FGF2 fold change with depressive and anxiety-like behaviors." (PMID 30273396, 2018). "Our findings may shed light on the participation of FGF2/FGFR1 signaling in determining anxiety and mood, where a neuronal role for FGFR1 has been hypothesized (Turner, Watson & Akil, 2012a)." (PMID 28439461, 2017). "Furthermore, increased anxiety, dysregulation of the hypothalamic pituitary axis and decreased hippocampal glucocorticoid receptor expression is observed in FGF2 knockout mice." (PMID 28439461, 2017). "Importantly, replacing FGF2 in the brains of anxiety-prone animals reverses these tendencies, acts as an antidepressant and increases their activity and exploration." (PMID 23497694, 2013). "Further evidence suggests that levels of fibroblast growth factor 2 (FGF2) in the hippocampus are decreased in animals with higher anxiety and lower response to novelty and that early life administration of FGF2 is able to prevent increased anxiety in later life." (PMID 23785661, 2013). "Thus, animals that are prone to anxiety and depression, like depressed humans, have low levels of FGF2." (PMID 23497694, 2013). "Interestingly, early life treatment with FGF2 may decrease anxiety-like behaviour in adulthood, which probably involves an interaction between FGF receptors and adenosine A2 receptors or dopamine D2 receptors." (PMID 33860438, 2021). "However, mice with genetic ablation of FGF2 isoforms do not show alterations of anxiety-like stress susceptibility." (PMID 33860438, 2021). "While this phenotype may result from impaired local oligodendrogenesis, knocking down FGF2 expression in prefrontal cortical OPCs recapitulates the anxiety-like phenotype, suggesting that FGF2 release from OPCs is a critical regulator of circuit function in this region." (PMID 30524235, 2018). "For example, FGF2 has been hypothesized as an “on-line” modulator of mood and anxiety in adults." (PMID 24672476, 2014). "Further analysis revealed that FGF2 restored glutamate uptake in astrocytes via the JAK/STAT pathway and improved fear and anxiety-like behavior in a rat model of PTSD." (PMID 38288836, 2024). "To test this, we employed a rodent model of depressive behaviour, chronic variable stress (CVS) in conjunction with antidepressant treatment (fluoxetine) in wild-type (WT) and FGF2 knockout mice (FGF2KO) and examined depressive and anxiety behaviors." (PMID 30273396, 2018).
Anxiety (continued). "In another model of PTSD that involves single prolonged stress (SPS), FGF2 administration was shown to inhibit SPS-induced hyperarousal and anxiety behavior, symptoms resembling PTSD." (PMID 26733803, 2015). "Similarly, the FGF2 knockout was reported to increase hypothalamic-pituitary-adrenal axis (HPA) activity and anxiety behavior in mice." (PMID 30804785, 2019). "FGF2 is mainly synthesized in astrocytes, and its administration ameliorated anxiety and arousal symptoms in an animal model of PTSD; conversely, other investigators have highlighted that increased FGF2 levels trigger reactive astrogliosis, suggesting a role for FGF-2 in CNS injury." (PMID 38796504, 2024). "Exogenous FGF2 reduces stress-induced changes in astrocytes which may be a pathway to regulation of anxiety-like behavior; however, anti-anxiety-like effects of FGF2 in mice do not require FGFR1 or R2." (PMID 36906620, 2023). "Research has shown that intraperitoneal injection of FGF2 can block the SPS-induced PTSD fear response and anxiety behavior via astrocytic but not neuronal mechanisms." (PMID 38288836, 2024). "While it is not clear how each of these growth factors uniquely contributes to modulating depressive and anxiety-like behaviors, unlike BDNF and VEGF, FGF2 is largely produced by astroglial cells, and the effects of FGF2 on neuroplasticity are typically mediated through astroglial cells." (PMID 30273396, 2018).
atherosclerosis (30 papers, 2011 to 2025). A disease characterized by the build-up of fatty material and calcium deposition in the arterial wall resulting in partial or complete occlusion of the arterial lumen. "The primary aged CAVSMCs and HGPS VSMCs exhibit elevated levels of FGF2, which is associated with atherosclerosis." (PMID 38576084, 2024). "Because oxLDL and homocysteine are both risk factors for atherosclerosis, the possibility remains that they synergistically promote EC cytotoxicity through a shared pathway related to FGF2." (PMID 24490960, 2014). "Because circulating oxLDL and MDA-LDL levels are greatly increased in individuals who have coronary events, FGF2 downregulation by oxLDL may be an important mechanism underlying the impaired angiogenic response in atherosclerosis." (PMID 24490960, 2014). "DNMT3b can also reduce the expression of fibroblast growth factor 2 and promote atherosclerosis by increasing DNA methylation in endothelial cells." (PMID 35422896, 2022). "Intima and media thickening in atherosclerosis progression is an evidence that overproliferation of VSMC induced Fibroblast Growth Factor-2 (FGF-2) and enhanced the cell migration in inflammation." (PMID 36093338, 2022). "Previous studies have shown that VEGFA, EGFR, and FGF2 are related to vascular endothelial regeneration, and that vascular endothelial cell damage is a significant feature of atherosclerosis." (PMID 36212940, 2022). "As a long-considered risk factor for atherosclerosis, homocysteine can exhibit synergistic EC toxicity with modified LDL by a shared pathway related to fibroblast growth factor (FGF)-2." (PMID 29433446, 2018). "In contrast to polymorphisms in FGF2 and EGF, polymorphism rs35767 in the IGF1 gene was studied in the context of atherosclerosis; however, data are scarce." (PMID 27835972, 2016). "Aberrant methylation of genes like SOD2 and FGF2 contributing to atherosclerosis in T2DM." (PMID 38323108, 2024). "In chronic inflammatory diseases such as atherosclerosis and chronic arthritis, FGF2 functions as a pro-inflammatory factor by activating macrophages or cooperating with IL-17, whereas in influenza A virus (IAV) infection, FGF2 protects against acute lung injury by recruiting neutrophils." (PMID 35093168, 2022). "Short-term stimulation of VSMCs with FGF-2 can cause a transient increase in TSP-1 (Thbs1) expression, which may be one of the ways FGF-2 promotes atherosclerosis." (PMID 35811717, 2022). "Although the presence of FGF1 and FGF2 as well as their receptors has been shown on atherosclerotic arteries of rat and human origin, only very few studies have addressed the role of these receptors during the early phases of atherosclerosis development." (PMID 24224032, 2013). "As the role of FGF in atherosclerosis is much less documented than its role in restenosis, we checked the presence of FGF and its receptors in atherosclerotic lesions of apoE-deficient mice and found high expression of FGFR1 and the FGFR ligands FGF1 and FGF2." (PMID 24224032, 2013). "Several extracellular matrix molecules, besides PTX3, are able to trap FGF2 in the extracellular environment (such as thrombospondin-1 and cleaved syndecan) and modulate its effects during processes such as inflammation, wound healing, atherosclerosis, and neoplasia." (PMID 29556234, 2018). "It promotes vascular endothelial cell proliferation via interaction with fibroblast growth factor-2 (FGF-2) and exhibits anticoagulant activity by binding to antithrombin III to prevent the initiation and progression of atherosclerosis." (PMID 41303456, 2025). "Aberrant methylation of several genes, including SOD2, FGF2, ABCA1, COX2, and SMAD7, have been identified as key progressor of T2DM-related atherosclerosis." (PMID 38323108, 2024).
atherosclerosis (continued). "C. pneumoniae infection of cultured endothelial cells has been reported to increase FGF2 and PDGF production, which may be responsible for smooth muscle cell proliferation and intimal thickening in aortic tissues, and could account for its potential association with atherosclerosis." (PMID 21998584, 2011). "Indeed, both an antibody against FGF2 and an FGFR tyrosine kinase inhibitor (SU5402) have been shown to inhibit SMC proliferation in the setting of vascular injury or atherosclerosis." (PMID 27189169, 2016). "FGF-2 is produced by VSMC, participates in proliferation, hypertrophy, migration to the intima and synthesis of extracellular matrix of VSMC after activation as a powerful mitogen, and plays crucial role in atherosclerosis." (PMID 22997500, 2012). "High expression of VEGF-A/VEGFR-2 and FGF-2/FGFR-1 but not of PDGF-BB/PDGFR-β may contribute to immature and inflammatory intraplaque angiogenesis and plaque instability in a rabbit model of atherosclerosis." (PMID 30125282, 2018).
leukemia (29 papers, 2010 to 2025). A malignant (clonal) hematologic disorder, involving hematopoietic stem cells and characterized by the presence of primitive or atypical myeloid or lymphoid cells in the bone marrow and the blood. "The microarray data may provide clues about the mechanisms underlying FGF2 mediated support of the growth and survival of leukemia cells in the BM." (PMID 27481339, 2016). "The FGF-2 test in leukemia was completely excluded from the statistical analysis due to the lack of statistical significance of the ROC analysis." (PMID 38473833, 2024). "In vivo, 6TG prevented neovascularization stimulated by VEGF, FGF2, or human leukemia cells (LIK) in the chick embryo chorioallantoic membrane." (PMID 38590636, 2024). "In our 3D BM niche-like AML model, leukemia cells demonstrated an upregulation of FGF2, FOS, and ERBB2, which acts on and activates Twist1 and Snail2." (PMID 37932837, 2023). "Increased levels of FGF2 and FL support the survival of residual leukemia cells during gilteritinib treatment, thus inducing early resistance and catalyzing late resistance." (PMID 36691065, 2023). "FGFR1 and 2, the receptor of FGF2, were differently expressed in leukaemia cells co-cultured with MSCs from different origin and FGFR2 expression was significantly increased in leukaemia cells co-cultured with MSCs from T-ALL mice after PCR validation." (PMID 36333298, 2022). "For instance, targeting FGFR with the inhibitors PD173074 and BGJ398 (infigratinib) suppresses the exosomal secretion of FGF2 and protects leukemia cells from tyrosine kinase inhibitors." (PMID 36320056, 2022). "It has been demonstrated that fibroblast growth factor 2 (FGF2)-enriched exosomes from bone marrow stromal cells are endocytosed by leukemia cells (AML) and protect leukemia cells from tyrosine kinase inhibitors (TKIs)." (PMID 33805807, 2021). "We also show that stimulation of leukemia cells with FGF2 increases nuclear level of FGFR2 in its phosphorylated form, as well as HOXA9 and MEIS1 expression." (PMID 33924850, 2021). "Electroconvulsive therapy releases ATP from astrocytes to induce leukemia inhibitory factors and fibroblast growth factor 2, which leads to antidepressive actions." (PMID 35069121, 2021). "In leukemia, bone marrow stromal cell-derived exosomes carrying fibroblast growth factor 2 (FGF2) can be endocytosed by leukemia cells, endowing the leukemia cells with protection from tyrosine kinase inhibitors." (PMID 33168028, 2020). "Leukemia cells that had taken up FGF2 in this way were better able to survive kinase inhibitor treatment than leukemia cells that had not." (PMID 30720426, 2019). "FGF2 is an autocrine signaling protein for stroma, but recombinant FGF2 also mediates paracrine protection of leukemia cells." (PMID 30720426, 2019). "How FGFR1 is positioned in the exosome membrane (inside or out), how FGF2 binds FGFR1 in exosomes, and how exosomal FGF2 activates FGFR1 in leukemia cells, are areas of active investigation." (PMID 30720426, 2019). "(E) Model of bone marrow stromal FGF2 autocrine signaling and paracrine protection of leukemia cells by FGF2-containing exosomes." (PMID 30720426, 2019). "FGF2 has also been shown to be essential for stress hematopoiesis after chemotherapy, suggesting that leukemia cells can hijack a normal marrow stress response for their own survival." (PMID 30720426, 2019). "Here, we provide direct evidence that FGF2 facilitates the growth and survival of leukemia cells in the BM, even though the direct effects of FGF2 on leukemia cell growth were minimal." (PMID 27481339, 2016). "In vitro, FGF2 significantly decreased the number of stromal-dependent and stromal-independent G0-leukemia cells in the stromal layers." (PMID 27481339, 2016). "To address this issue further, we evaluated mesenchymal stromal cell and osteoblast mediated support of leukemia cell growth after FGF2 exposure." (PMID 27481339, 2016).